NLRP3 (NLR family pyrin domain containing 3)
Diseases named in the same sentence as NLRP3 in open-access papers (continued):
Sharing a sentence is not in itself a finding about the gene and the disease.
diabetic cardiomyopathy (100 papers, 2014 to 2026). Diabetic cardiomyopathy is a disorder of the heart muscle in people with diabetes. "For instance, in models of diabetic cardiomyopathy, NLRP3 activation was associated with both QT prolongation and the heightened inducibility of ventricular tachycardia, reversible by inflammasome inhibition." (PMID 40649732, 2025). "A recent study also found that GAS5 is involved in regulating the pathophysiological process of diabetic cardiomyopathy caused by NLRP3 inflammasome activation." (PMID 38561456, 2024). "The suppression of NLRP3 inflammasome via Rosuvastatin has been implicated in the treatment of diabetic cardiomyopathy." (PMID 39337693, 2024). "By pharmacological intervention with IL-1βR antagonist or NLRP3 inhibitor, cardiac arrhythmias were ameliorated, which indicated that activation of NLRP3 inflammasome was implicated in diabetic cardiomyopathy." (PMID 37336361, 2023). "For this reason, it is important to further explore the precise pathogenic link between NLRP3 inflammasome/pyroptosis and diabetic cardiomyopathy in the hope that this endeavor translates into promising therapeutic approaches for the sufferers of DCM." (PMID 36142531, 2022). "Low chronic inflammation in the myocardium is one of the main causes of diabetic cardiomyopathy; hence, the inhibition of NLRP3 inflammasome-mediated inflammation can effectively improve diabetic cardiomyopathy." (PMID 35563208, 2022). "NcRNAs influence the susceptibility to the pathogenesis of diabetic cardiomyopathy by mediating NLRP3 inflammasome activation-induced pyroptosis." (PMID 36111168, 2022). "The nucleotide-binding oligomerization domain-like receptor family, pyrin domain-containing 3 (NLRP3) inflammasome is associated with the development of diabetic cardiomyopathy." (PMID 35408946, 2022). "Elmadbouh I and Singla DK found that diabetic cardiomyopathy involves sterile inflammation and causes the upregulation of NLRP3-Nek7-GBP5 inflammasome complex, which finally initiates Caspase-1-dependent pyroptosis in diabetic cardiomyopathy." (PMID 35509275, 2022). "Nucleotide-binding oligomerization domain-like receptor protein 3 (NLRP3) inflammasome is associated with metabolic disorder and cell death, which are important triggers in diabetic cardiomyopathy (DCM)." (PMID 25136835, 2014). "A pathophysiological role of the NLRP3 inflammasome has been also shown in animal models of injury due to anticancer treatments (i.e., chemotherapy and radiation therapy), obesity and age-associated metabolic derangements, diabetic cardiomyopathy, pericarditis, myocarditis, and cardiac sarcoidosis." (PMID 33673188, 2021). "Thus, the role of HMGB1 as TLR4 ligand and upstream inducer of NF-κB and NLRP3 may shape a key pathogenic axis in diabetic cardiomyopathy, suggesting their potential as novel anti-inflammatory approaches." (PMID 28659798, 2017). "It has been demonstrated in previous studies that the NLRP3 inflammasome contributes to the progression of diabetic cardiomyopathy (DCM), and that ICA exerts a protective effect in DCM." (PMID 42292806, 2026). "In accordance with our results, ticagrelor demonstrated a distinct therapeutic potential by modulating the NLRP3 inflammasome in the progression of diabetic cardiomyopathy in mice." (PMID 40622464, 2025). "Although atrial remodeling has been more extensively characterized, growing evidence suggests that similar NLRP3-driven electrophysiological alterations also occur in the ventricle, as demonstrated in both ischemic and diabetic cardiomyopathy models." (PMID 40649732, 2025). "Synergistic cardioprotective effects of TIL and syringin in diabetic cardiomyopathy through the interaction between the TLR4/NF-κB/NLRP3 and PGC1α/SIRT3 pathways have also been documented." (PMID 39388398, 2024). "As the core of the whole response, NLRP3 and Caspase-1 are considered as markers and targets of pyroptosis in diabetic cardiomyopathy." (PMID 39545058, 2024).
diabetic cardiomyopathy (continued). "SMI can inhibit the high-fat-induced activation of the NLRP3/Caspase-1 signaling pathway, intervene in cardiomyocyte pyroptosis, and prevent diabetic cardiomyopathy." (PMID 38027923, 2023). "It has been reported that the NLRP3 inflammasome-mediated classical pyroptosis signaling pathway is a key driving force in diabetic cardiomyopathy." (PMID 37958991, 2023). "Previous studies have demonstrated the involvement of the NF-κB/NLRP3 inflammasome signaling pathway in regulating pyroptosis in various diseases, such as spinal cord injury, diabetic cardiomyopathy and Aspergillus fumigatus keratitis." (PMID 37628889, 2023). "Krill oil inhibits NLRP3 inflammasome activation by upregulating the expression of SIRT3 and PGC-1α and prevents the pathological injuries associated with diabetic cardiomyopathy." (PMID 37196115, 2023). "Given that AS-IV can inhibit NLRP3 inflammasome activation in DN glomeruli and according to previous reports, klotho can improve diabetic cardiomyopathy by inhibiting the NLRP3 inflammasome pathway." (PMID 37261217, 2023). "Another study also verified that BMP7 relieves pyroptosis induced by NLRP3 inflammasome in the setting of diabetic cardiomyopathy." (PMID 36858954, 2023). "H2S deficiency aggravated mitochondrial damage, increased ROS accumulation, promoted necroptosis, activated NLRP3 inflammasome, and finally exacerbated diabetic cardiomyopathy in the hearts of mice." (PMID 35408946, 2022). "Accumulating evidence suggests that a variety of hypoglycemic agents possess the favorable properties of inhibiting the NLRP3 inflammasome activation or pyroptosis, thereby realizing the improvement of diabetic cardiomyopathy." (PMID 36142531, 2022). "GAS5 acts as a competing endogenous RNA to enhance AHR expression by sponging miR-34b-3p and repressing NLRP3 (inflammasome) activation-mediated pyroptosis to improve diabetic cardiomyopathy." (PMID 36061542, 2022). "In recent years, the role of the NLRP3 inflammasome in diabetic cardiomyopathy has drawn much attention." (PMID 35355717, 2022). "Overexpression of GAS5 can inhibit NLRP3 inflammasome activation-mediated pyroptosis, improve cardiac function and myocardial hypertrophy in diabetic cardiomyopathy mice." (PMID 35619068, 2022). "Lately, it has been reported that Cmklr1 axis contributed to the development of diabetic cardiomyopathy on inflammation, which was primarily mediated by Nlrp3 inflammasome." (PMID 35721719, 2022). "Recent studies have reported that NLRP3 inflammasome activation-mediated pyroptosis aggravates the formation and development of diabetes cardiomyopathy (DCM)." (PMID 36061533, 2022). "By activating NLRP3, stimulates the production of IL-1β and IL-18, triggers pyroptosis, and ultimately leads to the development of diabetic cardiomyopathy." (PMID 35355717, 2022). "Western blotting analysis demonstrated that Puer-V significantly suppressed the NLRP3-Caspase-1-GSDMD signaling pathway which was highly activated in the diabetic cardiomyopathy." (PMID 36361807, 2022). "BMP-7 treatment against inflammasome formation showed a significant reduction (p < 0.001) in the expression of TLR4 and NLRP3 as compared to the diabetic cardiomyopathy group." (PMID 34685620, 2021). "Animal studies have also shown that exercise suppresses NLRP3 inflammasome signaling in the aorta of obese mice, diabetic cardiomyopathy, and various brain regions, including the hippocampus, thus exerting protective effects against disease progression." (PMID 34943988, 2021). "Knockdown experiments using animal models of diabetic cardiomyopathy showed that noncoding RNAs, such as miRNA30d and lncRNA Kcnq1ot1, are important in mediating NLRP3 activation and pyroptosis, respectively." (PMID 32508013, 2020). "P2X7R mediates the accumulation of the NLRP3 inflammasome and is involved the development of diabetic cardiomyopathy." (PMID 33584279, 2020).
diabetic cardiomyopathy (continued). "The previous studies have shown that NLRP3 inflammasome-related pyroptosis plays a vital role in the development of diabetic cardiomyopathy." (PMID 31871948, 2019). "Excessive production of reactive oxygen species (ROS) and P2X7R activation induced by high glucose increases NLRP3 inflammasome activation, which contributes to the pathogenesis of diabetic cardiomyopathy." (PMID 29314607, 2018). "A study reported that the NLRP3 inflammasome contributed to the development of diabetic cardiomyopathy via ROS‐induced caspase‐1 and IL‐1β activation, which are the effectors of the NLRP3 inflammasome." (PMID 29314607, 2018). "In this regard, statins as rosuvastatin have also exhibited beneficial proprieties against diabetic cardiomyopathy through inhibition of NLRP3 inflammasome and mature IL-1β, via suppression of the MAPKs activation." (PMID 28659798, 2017). "The NLRP3 inflammasome, a member of the “NOD-like” (NLR) receptor proteins, is characterised by the presence of the pyrin domain and has been linked with the advancement of diabetic cardiomyopathy." (PMID 39129285, 2025). "They proposed that a chronic training intervention is an effective preventive and curative approach to ameliorate diabetic cardiomyopathy by modulating the NLRP3 inflammasome and subsequently reducing inflammation, a finding confirmed by our results (i.e., decreased IL1β and increased IL10 levels)." (PMID 38532054, 2024). "Furthermore, the treatment of type two diabetes mellitus model mice with 100 mg/kg/day ticagrelor for 12 weeks attenuated the progression of diabetic cardiomyopathy and reduced the expression levels of NLRP3, caspase-1, and GSDMD-N in the myocardium." (PMID 38188139, 2024). "Some studies observed that the NEK7/NLRP3 inflammasome-signaling pathway is involved in diabetic vascular injury or in inflammation-related diabetic cardiomyopathy, a type of sterile inflammation, with a role in oligomerization and activation of the NLRP3 inflammasome complex." (PMID 38338718, 2024). "Furthermore, Sun and Ding70 proposed that diabetic cardiomyopathy is an inflammatory disease exacerbated by NLRP3 inflammasome-mediated release of IL-1β and IL-18." (PMID 38532054, 2024). "Similarly, in mice with streptozotocin (STZ, 60 mg/kg, ip)-induced diabetes mellitus, SIRT3 deletion resulted in the upregulation of inflammatory mediators such as NLRP3, caspase-1 p20, and IL-1 β, ultimately exacerbating diabetic cardiomyopathy." (PMID 37196115, 2023). "Cathepsin B exacerbates diabetic cardiomyopathy by promoting NLRP3-mediated pyroptosis." (PMID 37766966, 2023). "However, LncRNA GAS5 inhibits NLRP3 (inflammasome) activation-mediated pyroptosis in diabetic cardiomyopathy by targeting miR-34b-3p/AHR." (PMID 36061542, 2022). "However, there are few studies on the mechanism of NLRP3 inflammasome/pyroptosis in AS combined with diabetic cardiomyopathy." (PMID 36142531, 2022). "In addition, syringin has been reported to exert cardioprotective effects in diabetic cardiomyopathy through the interaction of TLR4/NF-κB/NLRP3 and PGC1a/SIRT3 pathways." (PMID 35806462, 2022). "The NLRP3 inhibitors prevent the development of diabetic cardiomyopathy." (PMID 36320147, 2022). "Targeted inhibition of the NLRP3 inflammasome through probiotics may have the potential to prevent or suppress diabetic cardiomyopathy." (PMID 36111168, 2022). "However, in vivo and in vitro, exogenous H2S significantly improved diabetic cardiomyopathy, alleviating oxidative stress, necroptosis and the NLRP3 inflammasome." (PMID 35563208, 2022). "In addition, previous reports found that AMPK also inhibits NLRP3 inflammasome activation in a mouse model of diabetic cardiomyopathy and acute pancreatitis." (PMID 34531748, 2021).
diabetic cardiomyopathy (continued). "Here, we report inflammation-induced cell death mediated by inflammatory cells (macrophage and dendritic cells) and inflammasome formation (TLR4, NLRP3) and NLRP3 activators (Nek7 and GBP5) that cause cardiac cell death is the key player in the development and progression of diabetic cardiomyopathy." (PMID 34685620, 2021). "When animals were given rosuvastatin both NLRP3 inflammasome and MAPK expression was decreased, with associated decrease in cardiac fibrosis, suggesting a potential role for the NLRP3 inflammasome in diabetic cardiomyopathy." (PMID 32596261, 2020). "Recent evidence has shown that high glucose could promote NLRP3 inflammasome-mediated collagen synthesis, leading to caspase 1 activation and IL-1β secretion, which ultimately contribute to cardiac fibrosis in diabetic cardiomyopathy." (PMID 31354519, 2019). "Although no studies to date have investigated fibroblast-to-myofibroblast differentiation in the setting of diabetic cardiomyopathy, it remains possible that the NLRP3 axis may represent a useful therapeutic target to limit this process." (PMID 29515457, 2018). "NLRP3 inflammasome activation plays an important role in diabetic cardiomyopathy (DCM), which may relate to excessive production of reactive oxygen species (ROS)." (PMID 29993180, 2018). "It was observed that the hearts of mice suffered from severe diabetic cardiomyopathy due to a shortage in hydrogen sulfide (H2S), which further escalated mitochondrial damage, enhanced the buildup of ROS, facilitated necroptosis, and triggered activation of the NLRP3 inflammasome." (PMID 39129285, 2025). "Protocatechualdehyde (compound 4) was identified as a potential component that ameliorated streptozotocin-induced diabetic cardiomyopathy in mice through inhibiting the activation of the NLRP3 inflammasome; this may also contribute to PD treatment through its anti-inflammatory activity." (PMID 39519801, 2024). "However, it is unclear whether PPAR-γ can act on NLRP3 inflammasome in macrophages in the context of diabetic cardiomyopathy." (PMID 36142531, 2022). "Interestingly, treatment with BMP-7 attenuated the increased expression of Nek7 (p = 0.038) and GBP5 (p = 0.01) compared to the diabetic group, suggesting that BMP-7 attenuates inflammasome protein regulators Nek7 and GBP5 prior to the initiation of NLRP3 upregulation in diabetic cardiomyopathy." (PMID 34685620, 2021). "Therefore, the present study investigates whether diabetic cardiomyopathy involves sterile inflammation and causes the upregulation of NLRP3-Nek7-GBP5 inflammasome complex, which finally initiates caspase-1-dependent pyroptosis in diabetic cardiomyopathy." (PMID 34685620, 2021). "Furthermore, Rosuvastatin, a 3-hydroxy-3- methylglutaryl coenzyme A reductase inhibitor shown to have anti-inflammatory and anti-oxidant properties in several disease pathologies, conferred improvements in the setting of diabetic cardiomyopathy, via an NLRP3 inflammasome-dependent mechanism." (PMID 29515457, 2018). "In diabetic cardiomyopathy (DCM), the combination of TIL and Syringin significantly reduced the expression of NLRP3, TNF-α, IL-1β, and IL-6 and attenuated myocardial injury." (PMID 39388398, 2024). "In this study, we studied the effects of PRR on cardiomyocytes treated with high glucose and on myocardial pyroptosis in rats with diabetic cardiomyopathy, and further explored the possible mechanism of PRR participating in AMPK/NLRP3." (PMID 39545058, 2024). "LncRNA GAS5 is down-regulated in cardiomyocytes with diabetic cardiomyopathy (DCM), and its overexpression suppresses the expression of NLRP3 and its downstream genes and caspase-1 activity, thus improving DCM." (PMID 37498354, 2023). "Dapagliflozin, another family member, alleviated diabetic cardiomyopathy by inhibiting NLRP3 through activation of the AMPK system and blocked the TXNIP/NLRP3 pathway." (PMID 37175869, 2023).
diabetic cardiomyopathy (continued). "Gypenosides can improve diabetic cardiomyopathy and CHD by inhibiting reactive oxygen species-mediated NLRP3 inflammasome activation." (PMID 34149404, 2021). "Image quantification showed a significant increase of TLR4 (p < 0.001) and NLRP3 (p < 0.001) expression levels in cardiac myocytes in the STZ-induced diabetic cardiomyopathy group compared to the control." (PMID 34685620, 2021). "Similarly, the suppressive effects of berberine on the NLRP3 inflammasome and GSDMD have been demonstrated in diabetic cardiomyopathy." (PMID 40142262, 2025). "In this study, we found that miR-223-3p, as a regulator of the pyroptosis molecule NLRP3, is downregulated in the myocardium of diabetic cardiomyopathy mice, but significantly increased after MSC treatment, thereby reducing the protein levels of NLRP3, Caspase-1, GSDMD, and IL-1β." (PMID 38956716, 2024). "Furthermore, a recent study found that dapagliflozin inhibited the NLRP3 inflammasome and activated AMPK, which protected against the progression of diabetic cardiomyopathy and cardiac fibrosis." (PMID 37681811, 2023). "However, treatment with BMP-7 attenuates the expression of TLR4 (p = 0.027) and NLRP3 (p = 0.033) compared to the STZ-induced diabetic cardiomyopathy." (PMID 34685620, 2021). "In the present study, we investigated a novel signaling target in diabetic cardiomyopathy where inflammation induces caspase-1-dependent cell death, pyroptosis, involving Nek7-GBP5 activators to activate the NLRP3 inflammasome, destabilizes cardiac structure and neovascularization." (PMID 34685620, 2021). "Therefore, we hypothesized that BMP-7 can inhibit the NLRP3 inflammasome complex and their activator Nek7-GBP5, and the subsequent cascade of pyroptosis in diabetic cardiomyopathy." (PMID 34685620, 2021).